HLA-G (major histocompatibility complex, class I, G)
Diseases named in the same sentence as HLA-G in open-access papers (continued):
Sharing a sentence is not in itself a finding about the gene and the disease.
cancer (continued). "However, with the HLA-G expression was observed in cancers for the first time in 1998, numerous studies have been carried out focusing on the basic biology and clinical significance of HLA-G in malignancies." (PMID 30234020, 2018). "Herein, we reviewed the literature on HLA-G heterogeneity in cancers, and the clinical implications of this heterogeneity that might be relevant to personalized treatments were also discussed." (PMID 30319626, 2018). "HLA-G expression by solid tumors has been associated with worse prognosis and higher grade in numerous cancers including but not restricted to kidney, ovary, breast, lung, colon." (PMID 30237859, 2018). "However, HLA-G expression can be switched on in various pathological conditions such as cancers, viral infection, organ transplantation, and autoimmune and inflammatory diseases." (PMID 30319626, 2018). "Furthermore, HLA-G heterogeneity in cancers has been related to disease stage and outcomes, metastatic status and response to different therapies." (PMID 30319626, 2018). "The anti-oncogenic role of Qa-2 is in deep contrast with the reported pro-tumorigenic function for HLA-G2, 5 (see also the Introduction), which raises the question whether Qa-2 is the functional murine homolog of HLA-G, at least in the context of cancer." (PMID 28740236, 2017). "Taken together, lesion HLA-G expression percentages in patients with CRC could be another prognostic factor which contributes an additional significance to the classical cancer TNM classification system." (PMID 29296176, 2017). "Cancer patients show enhanced expression of HLA-G/sHLA-G both locally and in the blood serum." (PMID 28376925, 2017). "It has been shown that hypoxia could play a role in HLA-G regulation during pregnancy, in some cancer but also in more physiologic but extreme life conditions like altitude." (PMID 26862036, 2016). "The HLA-G mediated tolerance is described in processes of pregnancy, inflammation, and cancer." (PMID 27199995, 2016). "HLA-G is an immune checkpoint molecule with specific relevance in cancer immunotherapy." (PMID 27577073, 2016). "A high frequency of HLA-G surface expression and high serum HLA-G concentration has been measured in both hematological and solid tumors, and it has been shown that the high expression of HLA-G and sHLA-G is correlated with a poorer prognosis in cancer patients." (PMID 27999823, 2016). "This opens for the possibility for considering HLA-G as an immune checkpoint molecule, and blocking the function of HLA-G may be a new therapeutic strategy in cancer immunotherapy." (PMID 27999823, 2016). "Using a process called trogocytose, wherein the plasma membrane and anchored proteins are transferred via cell-cell contact, the NK cells, dendritic cells, and T cells that receive membrane-bound HLA-G molecules from cancer cells, downregulate the immune response." (PMID 27999823, 2016). "Results from an in vitro study of samples from renal cell cancer patients indicate that HLA-G-peptide-based cancer immunotherapy may be possible." (PMID 27999823, 2016). "Therefore, regarding the growing and successful use of antibodies against checkpoints such as anti-CTLA-4 and anti- PD-L1/PD-1 to restore antitumor immunity, HLA-G appears as a wider and promising relevant target for cancer immunotherapy." (PMID 27577073, 2016). "HLA-G expression was firstly observed in cytotrophoblasts and its tissue distribution was very limited in physiological conditions; however, HLA-G can be neoexpressed in pathological conditions such as cancers 5,6." (PMID 25689063, 2015). "Notably, a recent study in human cancer (chronic lymphocytic leukemia) has reported an association with the +2960 14-bp INDEL polymorphism and plasmatic HLA-G protein levels and survival." (PMID 26633805, 2015).
cancer (continued). "HLA-G is highly expressed in physiological conditions in trophoblast at fetal-maternal interface and has a restricted distribution in normal tissues; however, an increased expression can be induced in pathological conditions such as cancer." (PMID 26633805, 2015). "Many studies have discussed the role of HLA-G and IL-17 in various types of cancer." (PMID 25351636, 2015). "Membrane HLA-G provides cancer cells a strong protection from immune cells." (PMID 26460949, 2015). "Of note: such demethylating agents are used in cancer therapy; they might therefore have the adverse effect of inducing immune escape through HLA-G expression." (PMID 25887663, 2015). "Thus cancers that have lost B2M still express both membrane and soluble HLA-G molecules able to interact with ILT4." (PMID 26460949, 2015). "However, HLA-G can be neo-expressed in pathological conditions such as transplantation, inflammatory and autoimmune diseases, viral infections, and cancers." (PMID 25887663, 2015). "The HLA-G gene repression can be reversed by demethylating agents used in some cancer therapies such as 5-aza-2′-deoxycytidine and inhibitors of histone deacetylases and may directly induce HLA-G cell surface expression." (PMID 24800261, 2014). "It is now clear that HLA-G is involved in promoting beneficial tolerance in several settings, such as autoimmunity and organ transplantation, and in contributing to detrimental tolerance in viral infections and cancer." (PMID 24741612, 2014). "The potential clinical relevance of HLA-G in cancer was previously addressed in several studies." (PMID 24870375, 2014). "New therapeutic approaches based on synthetic HLA-G-derived proteins or antibodies are emerging in mouse models of cancer or transplantation, and these new therapeutic tools may eventually prove useful for the treatment of infectious diseases." (PMID 24839609, 2014). "One recently considered hypothesis focuses on human leucocyte antigen-G (HLA-G), a tolerogenic protein involved in the control of immune response, due to its reported aberrant expression in a wide variety of cancer cells." (PMID 23265140, 2012). "Studies conducted in a variety of human cancer cell lines suggest that epigenetic mechanisms may play an important role in HLA-G expression." (PMID 18498645, 2008). "HLA-G exhibits limited genetic diversity and generates multiple isoforms that play a critical role in immune tolerance, being physiologically expressed in immunoprivileged tissues and aberrantly upregulated in a variety of pathological conditions, including cancer." (PMID 42083155, 2026). "Thus, a positive result with mAb 4H84 only indicates total expression of α1 domain–containing HLA-G isoforms and does not differentiate between splice variants or quantify their relative abundance in cancer lesions." (PMID 41194925, 2025). "In the context of precision medicine, it is therefore critically important to develop HLA-G isoform-specific antibodies to explore the clinical relevance of distinct HLA-G isoform expression in cancer patients, which could facilitate more precise HLA-G-targeted immunotherapeutic strategies." (PMID 41194925, 2025). "Cancer therapy may also have an impact on the expression of HLA-G." (PMID 38391781, 2024). "However, in cancer cells, it is unknown whether HLA-G activates STAT3 pathway via ILT4 or other yet unidentified protein partners." (PMID 36780531, 2023). "Furthermore, HLA-G gene expression can be induced by glucocorticoids or microenvironmental factors such as low oxygen tension or tryptophan starvation, both characteristic of cancer, along with it being regulated by epigenetic mechanisms." (PMID 37623251, 2023). "Moreover, due to the wide distribution of HLA-G receptors on all the immune cells, HLA-G could have the potential as a therapeutic target for the control of several cancer types." (PMID 37573450, 2023).
cancer (continued). "Therefore, HLA-G dimerization has great potential in cancer immunotherapy and may become a new target for cancer therapy." (PMID 37103820, 2023). "The expression of HLA-G is highly restricted in adults, but the de novo expression of this molecule may be observed in different hematological and solid tumors and is related to cancer progression." (PMID 35328349, 2022). "Accordingly, as with PD1/PDL1, an anti-HLA-G/ILT2 therapy could be effective for cancer treatment." (PMID 35154112, 2022). "Additionally, the HLA-G expression is also considered as the cancer-driving force with aggressiveness and metastasis potential in patients and preclinical models through the mechanism of overexpression of cancer metastasis-related factors, including MMPs." (PMID 36437782, 2022). "Indeed, HLA-G expression is an approved mediator of cancer immune evasion." (PMID 35681761, 2022). "Thus, HLA-G and its receptors might be targets for immune checkpoint blockade to restore immune cell function during cancer immunotherapy but still require further investigation." (PMID 34276642, 2021). "Based on these results, we agree that HLA-G might be a novel immune checkpoint in cancer." (PMID 34276642, 2021). "Indeed, HLA-G has been proposed as a new immune checkpoint in cancer." (PMID 34948104, 2021). "HLA-G or HLA-E could be valuable enhancers of immune responses in other cancers and for NK-cell targeted strategies, as shown for the anti-NKG2A blocking antibody monalizumab now developed as a novel first-in-class checkpoint inhibitor for HLA-E-positive cancers." (PMID 34201079, 2021). "Consequently, the additional analysis of factors that promote cancer invasiveness and metastatic progression, like the HLA-G 3’UTR haplotypes UTR-4, UTR-3, and UTR-7, might help to identify patients at a higher risk or with a favorable course more precisely." (PMID 35095919, 2021). "In theory, HLA-G isoform expression patterns may vary among and within carcinoma types." (PMID 34361031, 2021). "Therefore, HLA-G is a potential target for immunotherapy to treat cancer." (PMID 33213057, 2020). "Therefore, HLA-G and its receptors might be targets for immune checkpoint blockade in cancer immunotherapy." (PMID 32630545, 2020). "Interestingly, HLA-G expression is rarely found on in vitro established cancer cell lines." (PMID 32560316, 2020). "However, KIR2DL4-targeted drugs might enhance HLA-G-positive cancer progression, and patients treated with KIR2DL4 stimulants should first be carefully screened for the presence of malignancy." (PMID 32023940, 2020). "Therefore, combination blocking HLA-G with other immune checkpoints (PD-1/PD-L1 or CTLA-4) represents an inspiring strategy for cancer treatment, which may help overcome the resistance routinely developing in patients treated with a single immunotherapy." (PMID 33425752, 2020). "This immune inhibitory function of HLA-G could be hijacked by cancer cells to escape immune attack." (PMID 32222150, 2020). "Although the immune checkpoint molecule HLA-G has been associated with cancer invasiveness and metastatic spread in various malignant diseases, we were not able to correlate the total amount of sHLA-G to the clinical status or outcome of EOC patients in a previous study." (PMID 31382533, 2019). "Thus far, the importance of HLA-G in cancer promotion and progression has been widely acknowledged." (PMID 30234020, 2018). "Therefore, the level of HLA-G expression in malignant cells may vary according to the type of cancer." (PMID 30619504, 2018). "However, in cancer cells expressing HLA-G constitutively, hypoxia decreases HLA-G gene expression." (PMID 30061885, 2018). "Consequently, HLA-G as cancer immunotherapy target was proposed." (PMID 30234020, 2018). "Specific interventions that bypass HLA-G mediated immune escape, e.g. blocking antibodies against the HLA-G isoforms upregulated in EwS, may substantially improve efficacy of cellular therapies in this and other cancers." (PMID 29464090, 2018).
cancer (continued). "Besides the role of HLA-G in trophoblasts and placenta development, most human solid tumors contain hypoxic areas, and HLA-G expression has been documented in several types of cancer." (PMID 28781970, 2017). "In light of evidence from recent studies that HLA-G is a potent regulator of host immune defenses in patients with cancer and its impact in CRC survival, we hypothesized that HLA-G might confer tolerance to the inflammatory/immune status induced by drug treatments in CRC." (PMID 28653974, 2017). "Indeed, different proportion of lesion HLA-G expression has been found between different cancer types and also between tumors from individuals with the same type of cancer, and the prognostic significance of the different degree of HLA-G expression remains rather limited." (PMID 29296176, 2017). "Thereby, HLA-G might contribute to a reduced immune response against the tumors of cancer patients." (PMID 27999823, 2016). "In addition, polymorphic sites of HLA-G genes in cervical lesions and cancer have been studied." (PMID 25351636, 2015). "However, HLA-G molecule may counteract or elicit the progression of cancer as a consequence of its immune-modulatory properties regulated by SNPs present in the untranslated regions." (PMID 26633805, 2015). "Computational chemistry was used to optimize DSP216 affinity to HLA-G with the aim to achieve the desired binding mode and DSP216 binding to CD47+/HLA-G+ and CD47+/HLA-G- cancer cells, PBMCs, and RBCs was tested." (PMID 41662489, 2026). "Future research should focus on elucidating the mechanisms by which HLA-G and KIR interactions influence NK cell function and exploring how these pathways can be targeted for cancer immunotherapy." (PMID 41234446, 2025). "Overall, our findings suggest that HLA-G and KIR have the potential to be promising targets for future cancer immunotherapies." (PMID 41234446, 2025). "The promising strategy includes targeting the HLA-G/ILT signaling pathway alongside the use of CTLA-4/B7 and PD-1/PD-L1 as new immune checkpoints in cancer development." (PMID 39594832, 2024). "Thus, HLA-G may serve as a new biomarker of cancer development." (PMID 38391781, 2024). "A knowledge of the enhanced expression of HLA-G and ILTs in HNSCC progression should be used in cancer immunotherapy." (PMID 38391781, 2024). "By binding to HLA-G, ILT3 suppresses the immune response against cancer cells and promotes tumor growth." (PMID 38254772, 2024). "Nine modulated microRNAs targeting the BRAF, TERT, and/or HLA-G genes were observed in PTC and involved with cancer-related signaling pathways." (PMID 37569841, 2023). "Four immune checkpoint proteins, PD-L1, TLR4, HLA-G, and NKG2A, belong to the TMEM family and can form homodimers or heterodimers to regulate cancer immunotherapy." (PMID 37103820, 2023). "MicroRNAs play an important role in regulating anti-cancer immune responses via modulating of antigen processing and presentation, HLA-G expression, NKG2D ligands, PD-L1 level and metabolism in cancer cells." (PMID 37838685, 2023). "On the other hand, there is enough evidence that the HLA-G expression can be useful for the differential diagnosis between healthy controls, benign gastric diseases, and malignancies such as gastric, colon, esophageal, and lung cancer, and thus, it may be a useful biomarker for cancer screening." (PMID 37573450, 2023). "Metastatic spreading of cancer cells was evaluated by assessing the expression of human erythropoietin (EPO) and HLA class I histocompatibility antigen, alpha chain G (HLA‐G) in the lungs of mice injected with H/OSM or H/pCMV6 cells." (PMID 35064579, 2022). "HLA-G is an MHC-I molecule expressed on placental cells and cancer cells and potentially mediates immune tolerance." (PMID 35869114, 2022). "HLA-G CAR competes with inhibitory receptors of NK cells (LILRB1 and KIR2D4) to bind HLA-G on malignant tumors, contributing to the upregulation of phosphor-Syk/Zap70 and the downregulation of phosphor-SHP-1." (PMID 36428748, 2022).
cancer (continued). "Interestingly, HLA-G may be a potential new therapeutic target for cancer immunotherapy." (PMID 35027037, 2022). "The final goal is to interfere of the HLA-G/ILT-2 or ILT-4 immunological synapse and restore the host immune capacity to attack the cancer cells." (PMID 34773056, 2021). "Since a possible interplay between angiogenesis and immune-checkpoints has lately been evoked as a novel strategy to improve the success of cancer treatments, we ought to evaluate the potential co-expression of VEGF-A with the immune checkpoint HLA-G/ILT4." (PMID 32620162, 2020). "In conclusion, our novel cancer vaccination therapy comprising two peptides that bind multi-HLAs with Poly-ICLC and hLAG-3Ig adjuvants achieved highly effective induction of antigen-specific CTLs in patients with metastatic GI cancers." (PMID 32219501, 2020). "IFN-γ is one of the most potent transcriptional inducers of MHC class I genes; however, HLA-G transcriptional responses to IFN-γ has been inconsistently reported, possibly due to the near exclusive use of cancer cell lines in these studies." (PMID 32708387, 2020). "Therefore, HLA-G could act as a potential immune checkpoint for future anti-cancer immunotherapies." (PMID 32993793, 2020). "Cancerous cells secrete inflammatory cytokines like IL-10,IFN-γ which increase expression of immunosuppressive molecules, such as HLA-G." (PMID 32123232, 2020). "Here, we report a phase I study of cancer vaccination using a combination of two multi-HLA-binding peptides, HSP70 and GPC3, and the novel immune adjuvants combination of Poly-ICLC and hLAG-3Ig for patients with metastatic GI cancers." (PMID 32219501, 2020). "This evidence is derived from the results of a study that showed that HLA-G expression was significantly higher in CIN and cancer patients with HPV16/18 infections than in CIN patients without HPV infection." (PMID 32670296, 2020). "Understanding the structure of HLA-G, ILT and KIR receptors is crucial when studying the interaction and function of HLA-G receptor signaling in cancer." (PMID 33213057, 2020). "Currently, a clinical trial in phase I (NCT04485013) is underway targeting HLA-G by TTX-80, a monoclonal antibody, for patients with HLA-G-positive advanced cancers." (PMID 33425752, 2020). "Besides HLA-G isoform expression, polymorphic variants within the DNA sequence such as the 14 bp insertion/deletion in the 3′UTR might also have an impact on the overall increase of cancer risk due to its influence on mRNA stability and protein expression." (PMID 31013867, 2019). "Several current partially successful approaches for cancer therapy are in agreement with the i-CSC/p-ESC model, targeting crucial factors common to embryos and tumors, such as HSP70, HLA-G, ID, LIF/LIFr, and CD44." (PMID 30899759, 2019). "Our data demonstrated that HLA-G expression progressively increased from CIN1 to CIN2/3 lesions and was highest in patients with malignant cervical lesions." (PMID 30619504, 2018). "The purpose of this review was to examine original in vitro studies carried out in human cancer cell lines, which reported data about HLA-G expression and HIF-1 mediated-HLA-G expression in response to hypoxia." (PMID 28781970, 2017). "While most previous studies focused on the cancer itself, weak or absent HLA-G expression in PTTs has only been reported in a few studies with rather limited samples." (PMID 41181133, 2025). "Our findings also suggest that HLA-G and KIR molecules could represent valuable therapeutic targets for future cancer immunotherapy strategies." (PMID 41234446, 2025). "Complementary approaches could also focus on γδ T cells, especially in MMRd cancers with MHCI defects 47, DCs 29,48, PD-1 and PI3K-γ expressing myeloid cells 49,50, the HLA-E and HLA-G molecules 20,35,51–56, WRN inhibitors 57 or TREM1 myeloid cells." (PMID 40027748, 2025).